CD4 (CD4 molecule)
Diseases named in the same sentence as CD4 in open-access papers (continued):
Sharing a sentence is not in itself a finding about the gene and the disease.
infection (continued). "IFN© production by CD4+ and CD8+ T cells is crucial for protective immunity and overall survival of Tg infected animals although it is important to remember that there is a key contribution by inflammatory neutrophils and monocytes early in infection." (PMID 38950025, 2024). "Moreover, vaccine-induced S-specific CD4+ and CD8+ memory T cells have a functional phenotype similar to that observed in response to natural infection and are predicted to be long-lived." (PMID 39460293, 2024). "However, studies performed by our group on the CHACS samples revealed an increased HIV-DNA reservoir in the CD4+ T-cells of TPV+ versus TPV− HIV+, pointing to the possibility that Th17 depletion is a consequence of their infection." (PMID 38247848, 2024). "Women who spontaneously cleared infection without treatment exhibited increased CT-specific IFNγ+ CD4 T cells and were less likely to be reinfected when compared to women who required antibiotics for infection resolution." (PMID 39043447, 2024). "In the Discussion section, we state that Ca Ski subclones produced an adequate amount of HIV-1 RT corresponding to the levels of protein in a natural infection (although in the epithelial cells, not CD4+ T lymphocytes)." (PMID 38399969, 2024). "Antibodies (IgA and IgG), effector immune cells (CD4+ T cells, macrophages, and neutrophils) and cytokines (including IL-17A and IFN-ɣ) have been shown to play critical roles in regulating immune responses to S. pyogenes at the site of infection." (PMID 38576622, 2024). "Besides, we didn’t find any changes in the percentage of CD3+CD4+ and CD3+CD8+ cell populations by day 3 post-infection." (PMID 39001897, 2024). "nnAbs recognize productively infected cells only when CD4 is not completely downregulated, as is the case in infections with Nef-defective virus." (PMID 39373535, 2024). "This was accompanied by changes in cytokine profiles and parasite loads which were dependent on the cell type (CD4+ T, CD8+ T, NK, NKT and γδ T cells), the organ (SI, PP, MLN, SPL and liver), the time-point (day 5 and 10 post-infection) and the cytokine (IFNγ, IL-4, IL-10 and IL-13) studied." (PMID 38950025, 2024). "In contrast to activated CD4+ and CD8+ T cells for which infiltration peaked at day 10, the number of activated regulatory T cells was highest at day 14 at the site of infection, where they strongly upregulated expression of the anti-inflammatory cytokine IL10." (PMID 38898278, 2024). "Here we observed that IFN-α and IFN-β expression levels were not correlated with biomarkers of disease progression like CD4 T-cell count, viral load or peripheral T-cell activation during the course of infection." (PMID 39104769, 2024). "Despite a significant increase in neutralizing antibodies following the breakthrough infection, CD4+ and CD8+ responses were not boosted to levels observed in another study." (PMID 37112825, 2023). "Patients with HM had a significant rise (P = .02) in the frequency of spike-specific activated CD134+CD137+CD4+ T cells post–BT infection but not spike-specific activated CD69+CD137+CD8+ T cells (P = .77)." (PMID 38023562, 2023). "Moreover, in the context of the same infection, the kinetics of type I IFN signaling can have opposing effects on CD4+ T cell fates." (PMID 38274806, 2023). "For instance, incomplete CD4 T-cell restoration and low CD4:CD8 ratios may impede the development of anti-SARS-CoV-2 immune responses following vaccination and infection, especially before booster vaccination." (PMID 36851789, 2023). "As a control, infection of CD4+ DC did not exhibit chemotactic activity, irrespective of rXCL1 addition, as expected." (PMID 38077365, 2023). "We observed that during the pre-vaccination period, some individuals without a history of natural infection had detectable SARS-CoV-2-specific CD4+ T cells." (PMID 37575243, 2023).
infection (continued). "We were particularly interested to see that in most cases CD4 T cells do not release detectable EV during homeostasis, yet following immune challenge by infection or vaccination nearly all donors had detectable CD4+ EV." (PMID 37520724, 2023). "These infections should be routinely monitored with HIV viral load and the CD4/CD8 ratio." (PMID 37887742, 2023). "Infection with S. Typhimurium ΔRibD/H and administration of IL-23 skewed the population towards CD4, CD8 double negative MAIT cells as well as an increase in MAIT17; whereas CpG combo yielded a larger population of CD8+ MAIT cells and a bias towards MAIT1." (PMID 37720229, 2023). "If the period of infection is not determined and matched between the two groups, patients infected relatively recently will likely display higher CD4+ T-cell counts than those having been infected for a much longer period." (PMID 38005875, 2023). "While a neutralizing antibody is largely responsible for prevention of SARS-CoV-2 infection, recovery from an established infection is likely mediated by both cytotoxic CD8 T lymphocytes to clear virus-infected cells and CD4 lymphocytes-mediated neutralizing antibody response." (PMID 36992395, 2023). "Additionally, except for at weaning prior to infection, the highest percentage of IFN-γ+ lymphocytes in peripheral blood were CD4+ T cells followed by CTLs at 2 and 4 wpi." (PMID 36992179, 2023). "According to our results, AIM+CD4+ T specific for alpha S1 peptides did not decrease significantly beyond 9 mo post-infection, unlike alpha N-specific and delta-specific CD4+ TSCM." (PMID 37046496, 2023). "In summary, infection but not model antigens was able to induce CD4+ T-cell cytotoxicity in vivo, and this phenotype was accentuated by administration of anti-CTLA4 antibody." (PMID 37161048, 2023). "We identified CD4+ and CD8+ memory T cells with proliferative (Ki67+) and cytotoxic functions (granzyme B+) that expanded following infection, which makes it likely that they target MAYV-infected cells." (PMID 37983245, 2023). "Of note, pre-incubation of HIV-1 particles with soluble Siglec-7 increased the infection rate of CD4 T cells, which do not constitutively express Siglec-7 at the surface." (PMID 37506557, 2023). "Compared with resting CD4 + T cells alone, none of the cytokine treatments induced additional infection." (PMID 37202790, 2023). "These individuals were initially referred to as “long-term non-progressors” (LTNPs) and were primarily classified based on the duration of infection and CD4+ T-cell count since viral load testing was not available until the mid-1990s." (PMID 37376660, 2023). "We additionally investigated spike-specific CD4+ and CD8+ T-cell responses in a subset of 24 individuals, including 8 older adults, who subsequently experienced their first SARS-CoV-2 breakthrough infection between 1 and 6 months after receiving 3 vaccine doses." (PMID 38035132, 2023). "In contrast, depletion of Gr1+ cells did not affect the frequency of CD4+ IL-4+ (Th2) cells but significantly increased this T-cell subset at week 2 of infection." (PMID 36776848, 2023). "We find that the infant rate of viral diversification varies by individual, gene region, and relative timing of infection, but not by set-point viral load or rate of CD4+ T cell decline." (PMID 38117834, 2023). "In 16 patients with mild breakthrough infection, there was no change in serum neutralization of Omicron BA.4/5, but there was an increase in CD4+ T cells postinfection." (PMID 38023562, 2023). "We conducted a cross-sectional study of SARS-CoV-2-specific CD4+ and CD8+ T-cell responses at several time points over 18 months (30–750 days) post mild/moderate infection with the aim to identify suitable methods and biomarkers for evaluation of long-term T-cell memory in peripheral blood." (PMID 37046496, 2023).
infection (continued). "A recent study showed that infection of neonatal mice with RSV resulted in airway hyperresponsiveness and increased numbers of eosinophils, macrophages, and CD4+ T cells in the lungs compared to mock-infected mice, demonstrating that recruited eosinophils can contribute to disease severity." (PMID 37896776, 2023). "TH1- and TH2-related transcripts included Nfatc1, Cd4, Runx3, and Gata3, suggesting that TH1 cells may be a significant contributor to interferon-gamma (IFNγ) production during infection in the adipose tissue." (PMID 37923768, 2023). "In the current study, we saw a 5-fold reduction in transmission rate after non-primary infection as compared to primary infection despite the presence of CD4+ T lymphocyte depletion–akin to a recent study in humans." (PMID 37796819, 2023). "Because the gut-homing CCR5+CD4+ cells that express the integrin receptor α4β7 are a potential target for HIV/SIV, their induction could fuel infection and decrease vaccine efficacy." (PMID 38005994, 2023). "After Omicron infection, CD4+T cell% had no obvious change in both cancer patients and non-cancer-afflicted subjects at the early stage but trended to decline at the late stage." (PMID 37035158, 2023). "Overall, our results showed that pre-existing CD4+ T cells provide strong cognate help during immunization or infection to enhance Ab production but not antigen-specific GC or memory B cells." (PMID 37711622, 2023). "However, the frequency and number of CD4+ and CD4+ CD25+ T-cells were significantly higher in the lungs of anti-Gr1-treated mice than in the control mice after 2 and 8 weeks of infection." (PMID 36776848, 2023). "γδ T cells in the peripheral blood of ART-treated patients harbour replication-competent HIV-1 DNA, and even following the reconstitution of CD4+ T cells, the frequency of these cells does not return to the pre-infection state." (PMID 37569570, 2023). "We repeated the study design but substituted primary infection studies in RhCMV-seronegative macaques with non-primary reinfection studies in CD4+ T lymphocyte-depleted RhCMV-seropositive macaques with naturally acquired RhCMV infection." (PMID 37796819, 2023). "Percentage of FAM-FLICA-/Live-dead- (FL-LD-), FAM-FLICA-/Live-dead+ (FL-LD+), FAM-FLICA+/Live-dead- (FL+LD-) and FAM-FLICA+/Live-dead+ (FL+LD+) CD4+ (G), CD8+ (H) splenic cells in vehicle (Vehicle, n=12) or VX-765 (VX-765, n=12) treated HIV-1 infected huNSG mice at day 22 post-infection." (PMID 36800238, 2023). "The percentage of CD28+CD95+ central memory CD4+ T cells (CD4+ Tcm) showed no significant change during infection, implying that naive CD4+ T cells differentiated into effector CD4+ T cells." (PMID 37033979, 2023). "While immune reconstitution and functionality of CD4+ and CD8+ T cells in the blood and tissues was greater in BLT mice compared to CCST mice, systemic and mucosal HIV-1 challenge of mice led to similar infection rates and viral replication." (PMID 37816950, 2023). "CD4+loIFN-γ and Ki67was highly significant in HIV (p<0.0001) infection." (PMID 37163092, 2023). "Prior to delving into the effects of infection on brain T cell responses, we elucidated the distribution of CD4 T cells within the non-inflamed CNS of SIV-uninfected macaques." (PMID 38060615, 2023). "The proportions of each scRNAseq identified subset within the CD4 T cells compartment did not significantly change between acute infection and post treatment timepoints." (PMID 37968278, 2023). "Next, we assessed whether the CD4 counts, CD8 counts, and CD4/CD8 ratio were altered by breakthrough infection in the study participants." (PMID 38140668, 2023). "The number of circulating CD4+ T cells was restored to basal levels from day 9 after infection in these animals but no significant cell proliferation occurred." (PMID 36906645, 2023).
infection (continued). "During the infection, subepithelial DCs present SARS-CoV-2-specific peptides through MHC class I and II molecules on the cell surface, thus promoting the activation of CD8+ and CD4+ T cells, respectively, which migrate to the lung after antigen exposure." (PMID 37662901, 2023). "CD4+ and CD8+ T cells are also activated during the course of infection." (PMID 37077528, 2023). "Finally, we incorporate analysis of antigen-specific CD4+ T cells found in blood from a cohort of HLA-DPB1*04+ human subjects following primary infection with SARS-CoV-2 and compare these responses to spike-specific memory CD4+ T cells found after vaccination." (PMID 37790414, 2023). "In separate donors, we detected importantly increased S1-specific CD4+ TSCM at the later stages post-infection and those who were not previously vaccinated." (PMID 37046496, 2023). "In contrast, elevated frequencies of activated CD4+HLA-DR+CD38+ T cells were seen in the LE group when compared to the control and asymptomatic infection group (median values of 5.56%, 5.55%, and 7.13%, p = 0.0166 in uninfected control., W. bancrofti-infected, and LE, respectively)." (PMID 37375499, 2023). "We found the same pattern at day 9 post-infection, with only aged CD4 T cells, but not CD8 T cells, having reduced frequencies compared to young cells." (PMID 37852965, 2023). "Studies in these infection models showed that when Bhlhe40 is absent in CD4+ T cells, IL-10 production increases, while IFN-γ production decreases." (PMID 37843306, 2023). "Even though PD-L1 was induced on the surface of the M1 macrophages at the early stage of infection, PD-1 expression was not significantly induced on CD4+ T-cells at the same time, until the eggs appeared in the liver at 6 weeks after infection." (PMID 36668953, 2023). "CD4+ T cell EMRA is a heterogeneous subset of effector memory T cells that reexpress CD45, provide protection against exposure to viral antigens and appear after the acute phase of infection." (PMID 36968223, 2023). "Infection with non-clade B viruses, CD4+ T cell counts <200 μl−1, being off ART and a longer time off ART were independent predictors of a more potent and broad neutralization." (PMID 37957379, 2023). "Previous studies have established that antigen-experienced T cells induced following infection can be tracked, regardless of their specificity, using CD11ahiCD49d+, and CD8αloCD11ahi surrogate markers for CD4+ and CD8+ T cells, respectively." (PMID 37669302, 2023). "Cytokines, including interleukin-6 (IL-6), interferon-inducible protein-10 (IP-10), and macrophage inflammatory protein 1 (MCP-1), were substantially elevated in blood and were correlated with activated CD4+ T cells, B cells, CD16+CD56+ NK cells, CD14+CD16+ monocytes during infection." (PMID 37033979, 2023). "Examination of Ifng gene expression in the spleen after infection did not reveal a significant difference in the expression of this gene between WT and Bhlhe40−/− splenocytes or splenic CD4+ T cells after infection." (PMID 37843306, 2023). "TCM, CD4+ TTM, CD8+ TN, and CD8+ TCM were found to have a significant negative correlation with the pre-infection CD4 counts in the BBIBP-CorV group." (PMID 38140668, 2023). "Nonetheless, two large longitudinal studies carried out in the USA found a higher rate of breakthrough infections in fully vaccinated PLWH; however, among them, high CD4 + T-cell counts (> 500/μL) and having received an additional dose were associated with a reduced risk." (PMID 36680700, 2023). "CD4 T cells with an IFN gene signature rapidly increase early after infection and return to normal levels within 3–7 days during nonlethal infection." (PMID 36445762, 2023). "Consistent with AIM assay results, there was a significant increase in spike-specific CD4+ tetramer+ T cells but not spike-specific CD8+ tetramer+ T cells in 10 patients with BT infection by TAME assay." (PMID 38023562, 2023).
infection (continued). "One month after infection the median frequencies of non-S-specific T cells using AIM were 1.48% for CD4 + T cells and 0.35% for CD8 + T cells." (PMID 37974069, 2023). "The levels of IgG, IgM, IgA and IgE of the CD4+T+CpG+Infection group were not significantly different from those of the CD4+ T+PBS group." (PMID 38151996, 2023). "How HBV establishes a chronic infection in those that progress to CHB remains unclear, but in acute HBV infection, HBV-specific CD4, CD8 T cells and neutralizing antibodies are key to limit the infection." (PMID 38140229, 2023). "Despite the absence of CD4+ T lymphocytes, RhCMV-seropositive macaques showed evidence of protection against cCMV transmission and infection." (PMID 37796819, 2023). "Even if pre-existing cross immunity by other HCoVs (human coronaviruses) to SCOV2 infection is debatable, there is accumulated evidence that HCoV-specific SCOV2 cross-reactive CD4+ T cells may trigger and enhance humoral immune responses in SCOV2 infection." (PMID 38077337, 2023). "CIR at 1.5 years after initial infection among PWH with CD4 count <200 was 21.2% (95% CI 13.7%–29.7%), among PWH with CD4 of 200–349 was 8.3% (95% CI 4.2%–14.2%), among PWH with CD4 of 350–499 was 9.7% (95% CI 6.2%–14.1%), and among PWH with CD4 ≥500 was 9.1% (95% CI 7.2%–11.2%)." (PMID 37877555, 2023). "Probably these existing CD4+TRMs may secrete IFN- γ and IL-2 upon SARS-CoV-2 infection and recruit CD8+ T cells into the site of infection for virus clearance." (PMID 36851616, 2023). "Infection also induces populations of airway spike-specific memory CD4+ and CD8+ T cells that are not expanded by vaccination alone." (PMID 37884506, 2023). "Since the depletion of CD4+ T cells seems to prevent effective priming of CD8+ T cells and favor the persistence of the infection, it is plausible that CD4+ T cells could be a possible source of IL-2." (PMID 37108816, 2023). "Direct infection by RSV and partial genetic dysfunction of the infant’s CD4+ T-cell response, however, may interfere with this balance, leading to a Th2-skewed immune response and more severe infections." (PMID 37896776, 2023). "Adoptive transfer of CD4+ T cells from the airways of RSV-infected mice into naïve mice reduced disease severity by suppressing the secretion of TNF-α compared to control mice, further supporting their protective role during infection." (PMID 37896776, 2023). "Like a previous report, cross-reactive SARS-CoV-2-specific CD4+ T cells from donors without a history of infection exhibited a TCM and TEM phenotype, indicating that they are most probably memory cells elicited by previous exposure to HCoVs." (PMID 37575243, 2023). "Similarly, lung CD4 and CD8 T cells increased their expression of Ifnγ at day 10 post-infection, matching their increase in cell number." (PMID 37842651, 2023). "At 1 month post-infection there were high levels of both CD4 + and CD8 + non-S-specific memory T cells (Median: 0.039% and 0.061%, respectively)." (PMID 37974069, 2023). "Of note, we observed detectable SARS-CoV-2-specific CD4+ T cells for the Wuhan S and R proteins in the pre-vaccination samples of some individuals without a history of natural infection and in some pre-pandemic samples." (PMID 37575243, 2023). "This contrasts with our data in the murine model that have demonstrated that Mo-MDSCs and PMN-MDSCs infiltrated the site of infection of L. sigmodontis-infected BALB/c mice and that only Mo-MDSCs exhibited suppressive capacities on the production of IL-13 and IFN-γ by CD4+ T cells." (PMID 37242335, 2023). "A decreased or inverted CD4+/CD8+ ratio represents poor immune status, which could be used as a predictor of severe infection or malignancy." (PMID 37942324, 2023). "Both QVD-OPH and ZVAD-FMK exhibited a dose-dependent suppression of infection with no significant adverse effect on cell toxicity nor the expressions of CD4 and CD62L." (PMID 36780482, 2023).